FOXA1 (forkhead box A1)
Diseases named in the same sentence as FOXA1 in open-access papers (continued):
Sharing a sentence is not in itself a finding about the gene and the disease.
breast tumors (continued). "Breast tumors with FOXA1 overexpression have been reported to have a good prognosis, and we expect that the expression of FOXA1 will be tested in AR-positive TNBCs in the future." (PMID 28067809, 2017). "GATA3 is thought to play a key role in making enhancer elements accessible to ER-α and its expression is highly correlated with both ER-α and FOXA1 in breast tumours." (PMID 25652398, 2015). "In contrast to GATA3 and FOXA1, the ZNF217 gene is amplified at 20q13 in ~20% of breast tumors and is associated with aggressive breast disease." (PMID 24962896, 2014). "The transcription factor GATA3 is a favorable prognostic indicator in estrogen receptor-α (ERα)-positive breast tumors in which it participates with ERα and FOXA1 in a complex transcriptional regulatory program driving tumor growth." (PMID 24758297, 2014). "GATA3 and FOXA1 are correlated with ERα positive breast tumors and are critical in normal mammary gland development in rodent models." (PMID 24339902, 2013). "Altogether, it seems that, in breast tumors, ER and AR binding and their functionality is fully dependent on FOXA1." (PMID 23192763, 2013). "ANP32E may function similarly in breast tumors, influencing the binding of key oncogenic transcription factors, such as FOXA1." (PMID 34922480, 2021). "In addition, a G>A mutational hotspot was discovered in ER+ breast tumors at position -81 relative to the FOXA1 TSS, resulting in increased binding of E2F1 and FOXA1 overexpression." (PMID 34831189, 2021). "Additionally, FOXA1 amplifications were observed exclusively in BC cases, rendering the dependence of breast tumors to FOXA1." (PMID 33102692, 2020). "Forkhead box protein A1 (FOXA1) is a pioneer factor that opens the compacted chromatin, facilitates the recruitment of ER to its genomic sites and co-expresses with ER during mammary gland development, and primary breast tumors development." (PMID 31496995, 2019). "Here we report the characterization of human breast tumors of both genders for cistromic make-up of hormonal regulation in human tumors, revealing genome-wide chromatin binding landscapes of ERα, AR, PR, GR, FOXA1, and GATA3 and enhancer-enriched histone mark H3K4me1." (PMID 29396493, 2018). "Breast tumors with positive ER–alpha and co-expressing PR-alpha were most likely to highly express DACH1, and nuclear DACH1 expression was positively correlated with luminal marker FOXA1 and inversely associated with basal-like markers EGFR13." (PMID 28659634, 2017). "The pioneer factor FOXA1 also plays an important role in androgen receptor (AR) signaling of molecular apocrine tumors, which have been recently identified as an additional subgroup of ER-negative and AR-positive breast tumors." (PMID 23192763, 2013). "Since ERα is one of the central genes for the regulation of growth/proliferation of mammary epithelia, and for the hormone-responsive phenotype of breast tumours, FOXA1 appears an important biological-regulatory factor with prognostic consequences in this setting." (PMID 19549328, 2009). "Hypermethylation of the LZTS1 transcription start site did not exhibit an association with expression in TCGA breast tumours; however, FOXA1 (R2 ≤ 0.75 and 0.67 for regions A and B, respectively) and CIRBP (R2 ≤ 0.212) both exhibited loss of expression with increased methylation." (PMID 25960784, 2015). "Strikingly, qPCR showed that KRT7 mRNA levels were increased by sevenfold and ninefold in the lung and breast tumors, respectively; meanwhile, the KRT7 downstream oncogenic forkhead box protein A1 (FOXA1) was markedly elevated." (PMID 37185462, 2023). "Accordingly, both depletion of FOXA1, and the chemical inhibition of IGF1‐R and AKT by MK‐2206, an AKT inhibitor in clinical trials for the treatment of breast tumors, in MCF‐7 cells all reduced the expression levels of each protein in the pathway." (PMID 36056637, 2022).
breast tumors (continued). "The top eight genes that negatively correlated to POLR3G expression (MLPH, FOXA1, SPDEF, AR, SIDT1, AGRP2, XBP1, GATA3) are typically overexpressed in ER+ breast tumors as compared to ER- breast tumors." (PMID 36497214, 2022). "Of the 35 upregulated genes, 5 were all related to breast tumor types: CASP8 (0.7-fold upregulation), CDH1 (1.21-fold upregulation), GATA3 (3-fold upregulation), ESR1 (3-fold upregulation) and FOXA1 (+ 2.89-fold upregulation)." (PMID 31182966, 2019). "As FOXA1 is one of the early events in the ER pathway activation cascade, it might be possible that the oncogenic nature of ER pathway activation is already established in early neoplasia and continues to IDC as FOXA1 and GATA3 are frequently mutated in ER+/luminal breast tumors." (PMID 29720211, 2018). "HOTAIR was shown to co-express with FOXA1 (forkhead box A1) and FOXM1 (forkhead box M1) in HER2-enriched breast tumors." (PMID 29469819, 2017). "Several overlapping genes especially the ones present in all datasets (ESR1, FOXA1, KRT17) are known to play critical roles in the subtyping and carcinogenesis of breast tumors." (PMID 26404658, 2015). "These signature genes are densely connected, among which several, such as ESR1, FOXA1, NQO1, GATA1, ALDH3B2, keratins, are well-known players driving the heterogeneity and carcinogenesis of breast tumors." (PMID 26404658, 2015). "The immunohistochemical evaluation of FOXA1 and GATA-3 in breast tumour samples revealed that in 201 of interpretable cases a very significant direct association between the expression of FOXA1 and GATA-3 was observed (P < 0.0001)." (PMID 19549328, 2009). "Several studies have shown that FOXA1 and GATA-3 expression are strong predictors of better clinical outcome in breast tumours and are among the best predictors of ERα-positive status." (PMID 19549328, 2009). "This revealed that both EPI (e.g. LLGL2, CLDN4, KRT7, ST14) and MES (e.g. SNAI1, VIM, AP1M1) genes positively correlated with PIEZO1 expression across all quintiles, whilst markers of luminal breast tumors (ESR1, FOXA1, PGR) negatively correlated in all instances." (PMID 38632473, 2024). "For example, back in 2000, it became known that treatment of breast tumor cells with retinoic acid leads to increased NIS expression, and one of the properties of retinoic acid, discovered in the field of developmental biology, is the enhancement of FOXA1 expression." (PMID 41155241, 2025). "The ER-estrogen-FOXA1-GATA-3 axis has a determining function in the beginning and/or progression of luminal-type tumors, and this has recently been proposed by the attestation of FOXA1 as a pioneer factor, essential for the expression of the bulk of estrogen-inducible genes, like a breast tumor." (PMID 37626655, 2023). "Indeed, while FoxA1 expression in ERα-positive primary breast tumors does not discriminate their metastasis-free outcome, elevated PBX1 expression has significant prognostic potential towards metastasis." (PMID 22125492, 2011).
hepatocellular carcinoma (45 papers, 2010 to 2025). A malignant tumor that arises from hepatocytes. "cDNA array analysis of the malignant hepatoma progression implicated a role for Foxa1, and silencing Foxa1 prevented the re-emergence of malignant and differentiation-associated gene expression." (PMID 27468690, 2016). "Taken together, function gain and loss experiments in hepatocellular carcinoma cell lines revealed that downregulation of FOXA1 accelerated cell proliferation, migration, and invasion, whereas FOXA1 overexpression suppressed the viability and motility of the cells." (PMID 29208003, 2017). "Here we used an integrative strategy to examine the hypothesis that genetic variants at FOXA1/2 binding elements may be associated with sexual dimorphism of hepatocellular carcinoma (HCC) risk." (PMID 25198130, 2014). "According to recent research, MCM3AP-AS1 acts as a ceRNA in hepatocellular carcinoma, functioning as a sponge for miR-194 to enhance FOXA1 expression." (PMID 38331968, 2024). "Upstream of Dio1, the oncogene astrocyte elevated gene-1 (Mtda) and the transcription factor forkhead box A1 (Foxa1) play an important role in reducing Dio1 expression in hepatocellular carcinoma." (PMID 36892852, 2023). "To exploit the role of FOXA1 in hepatocellular carcinoma cells, we determined the effect of FOXA1 on cell migration by wound healing and Transwell migration assays." (PMID 35968505, 2022). "FOXA1 also plays an important role in promoting cell proliferation and suppressing apoptosis in hepatocellular carcinoma." (PMID 34991620, 2022). "FOXA1 expression was significantly higher in hepatocellular carcinoma (LIHC), lung adenocarcinoma (LUAD), lung squamous cell carcinoma (LUSC), and cervical squamous cell carcinoma and cervical adenocarcinoma (CESC) than in the normal control group." (PMID 35968505, 2022). "To validate the role of FOXA1/2 in Rbfox2 regulation, we knocked down Foxa1 and Foxa2 in mouse hepatoma Hepa1-6 cells, which led to a significant decrease in Rbfox2 expression." (PMID 36536133, 2022). "MiR-3064-5p exerted an antiangiogenic role by targeting the FOXA1/CD24/Src pathway in hepatocellular carcinoma (HCC) but oncogenic lncRNA MALAT1 acted as a ceRNA to sponge miR-3064-5p." (PMID 34350110, 2021). "For instance, MCM3AP-AS1 promotes cancer cell growth in hepatocellular carcinoma by regulating the miR-194-5p/FOXA1 pathway." (PMID 34271873, 2021). "For example, miR-194-5p regulates FOXA1 by targeting and reversing the apoptosis and cell cycle arrest of hepatocellular carcinoma induced by MCM3AP-AS1 silencing." (PMID 34052838, 2021). "Another study reveals that MCM3AP-AS1 regulates the progression of hepatocellular carcinoma via miR-194-5p/FOXA1 axis." (PMID 34346845, 2021). "For example, MALAT1 functioned as a competing endogenous RNA (ceRNA) by sponging miR-3064-5p, which alleviated the suppressive effect on angiogenesis in human hepatocellular carcinoma via the FOXA1/CD24/Src pathway." (PMID 34012919, 2021). "Analyses of the mechanism and function revealed that FOXA1 suppresses hepatocellular carcinoma cell viability and motility by inhibiting PI3K/Akt signaling through direct inhibition of PIK3R1 transcription." (PMID 29208003, 2017). "Forkhead box A1 (FOXA1) expression is associated with various types of tumors; however, the function and underlying mechanism of FOXA1 in the development of hepatocellular carcinoma (HCC) remains obscure." (PMID 29208003, 2017). "Functionally, miR-212 was found to inhibit the growth of hepatocellular carcinoma by targeting FOXA1." (PMID 29190902, 2017). "It has been reported that FOXA1 positively regulates miRNA-122, which is correlated with favourable prognosis in human hepatocellular carcinoma." (PMID 24512546, 2014).
hepatocellular carcinoma (continued). "To overcome this functional redundancy, we investigated the role of Foxa1 in human hepatocytes and hepatoma cells by gain-of-function experiments and found that Foxa1 is a potent inhibitor of hepatic triglyceride (TG) synthesis and secretion." (PMID 22238690, 2012). "In the present study, we found that high levels of Foxa1 reduce steatosis in human hepatocytes and hepatoma cells." (PMID 22238690, 2012). "Our findings with the human colon cancer cell line Caco-2 agreed well with previous studies on the human hepatoma HepG2 cell line co-transfected with HNF6 or its deletion mutants as well as FOXA1, FOXA2, or FOXA3 TATA-luciferase reporter constructs." (PMID 20967225, 2010). "MCM3AP-AS1 promotes hepatocellular carcinoma growth by targeting the miR-194-5p/FOXA1 axis." (PMID 36672493, 2023). "FOXA1 is a key molecule in the occurrence and development of malignant tumors, which suggests that FOXA1 may play an oncogenic role in hepatocellular carcinoma." (PMID 35968505, 2022). "Indeed, studies in human hepatoma cell lines have shown that FoxA1 remains attached to chromatin during mitosis, contributing to rapid activation of downstream targets following mitosis during liver differentiation." (PMID 34156924, 2021). "Moreover, our study confirmed that MCM3AP-AS1 promotes hepatocellular carcinoma growth by targeting the miR-194-5p/ forkhead box A1 (FOXA1) axis." (PMID 33596983, 2021). "It is concluded that FOXA1 promotes cell proliferation and inhibits apoptosis, whereas FOXA1 is also found to suppress hepatocellular carcinoma cell viability and motility by transcriptional inactivation of phosphoinositide-3-kinase regulatory subunit 1 (PIK3R1) in PI3K/Akt signaling." (PMID 34336665, 2021). "Interestingly, HNF4G implies a negative regulation by interacting with FOXA1, RXRA, and HNF4A in the human hepatoma cell line and some studies have showed that interrelationships among FOXA1, FOXA2, HNF4A, and HNF4G affect transcriptional regulation." (PMID 29033978, 2017). "cDNA array and RT-PCR data in malignant hepatoma progression discovered Foxa1 as a potential checkpoint regulator, affecting a network of 224 genes that might be participants for the differentiation and malignant progression." (PMID 27468690, 2016). "Earlier studies have reported the role of sex hormones, transcription factors FoxA1/A2, and cytokine Il6 signaling in regulating the sex difference in hepatocellular carcinoma (HCC), but the role of metabolic pathways remains poorly understood." (PMID 41460563, 2025). "In this study, we investigated the expression of FOXA1 and its oncogenic role in hepatocellular carcinoma (HCC)." (PMID 35968505, 2022). "In hepatocellular carcinoma, MCM3AP-AS1 is upregulated and inhibits cancer growth by regulating the miR-194-5p/FOXA1 axis." (PMID 34271873, 2021). "During the development of hepatocellular carcinoma, MCM3AP-AS1 is upregulated and interacts with the miR-194-5p/FOXA1 axis to promote tumor growth." (PMID 34256796, 2021). "BoAA tumours had higher levels of miR1269b, which has been shown to be increased in hepatocellular carcinoma (HCC) and promotes HCC cell growth by down-regulating FOXA1." (PMID 29682207, 2018). "More importantly, FOXA1 and FOXA2 have been found to be essential for sexual dimorphic hepatocellular carcinoma (HCC) in mice." (PMID 29138513, 2017). "Moreover, by affecting the miR-194-5p/FOXA1 axis, MCM3AP-AS1 has been shown to increase hepatocellular cancer growth." (PMID 35992788, 2022). "In hepatocellular carcinoma, the lncRNA MCM3AP-AS1 could enhance cancer development by affecting the miR-194-5p/FOXA1 axis." (PMID 33023613, 2020). "However, upon culture, primary hepatocytes as well as hepatoma cells undergo substantial changes in gene expression patterns, including diminished production of key liver transcription factors such as C/EBPα and FOXA1 (also known as HNF3α)." (PMID 24367609, 2013).
hepatocellular carcinoma (continued). "Interestingly, recent studies on hepatocellular carcinoma have shown that FOXA1 can open up the dense chromatin surrounding the CREB binding site in the YAP promoter and promote CREB-mediated YAP transcription, leading to increased expression of YAP in HCC cells." (PMID 32411194, 2020).
bladder cancer (44 papers, 2012 to 2025). "KDM6A-deficient bladder cancer cell lines show a loss of interaction with FOXA1, normally involved in urothelial differentiation, and a redistribution of transcription factor ATF3, further repressing FOXA1-target genes and activating cell cycle progression." (PMID 38540132, 2024). "Increased UPK3B expression, decreased E-calcineurin expression, and increased cell proliferation have been observed in FOXA1-deficient RT4 bladder cancer cells, demonstrating a strong relationship between high UPK3B expression and tumor malignancy." (PMID 36681801, 2023). "In salivary duct carcinoma and bladder cancer, patients with high FOXA1 expression levels are associated with favorable clinical survival outcomes." (PMID 35273656, 2022). "To characterize the global transcriptional changes resulting from FOXA1 loss-of-function in bladder cancer cells, we performed whole transcriptome RNA sequencing of the parental UM-UC-1 cells and two FOXA1-KO sublines." (PMID 36323682, 2022). "Rather, lineage plasticity in bladder cancers with squamous differentiation is associated with loss of expression of FOXA1, GATA3, and PPARG, transcription factors critical for maintenance of urothelial cell identity." (PMID 36323682, 2022). "We found that lineage plasticity in bladder cancers with SqD was associated with loss of expression of the FOXA1, GATA3, and PPARG transcription factors." (PMID 36323682, 2022). "To identify the genes dysregulated by FOXA1 loss in a bladder cancer context, we next performed ChIP-Seq analysis of the parental UM-UC-1 and FOXA1-KO isogenic cells." (PMID 36323682, 2022). "Empirical evidence elaborated that loss of FOXA1 was an independent indicator of reduced overall survival in bladder cancer patients." (PMID 33323547, 2020). "For instance, FOXA1 is most frequently mutated in Breast and Bladder cancer, and ELMER identified it in these specific cancers." (PMID 25994056, 2015). "Downregulated gene products include putative tumor suppressor genes (SCUBE2), factors previously reported as lost in aggressive bladder cancer (FOXA1, GATA3, UPK3A), and metabolizing enzymes with polymorphisms affecting cancer risk (UGT1A10, UGT1A7)." (PMID 24134934, 2013). "Interestingly, overexpression of GATA3 and FOXA1 can influence the expression of markers associated with the luminal molecular subtype of bladder cancer, suggesting potential molecular connections in UTUC." (PMID 38425344, 2024). "Loss of FOXA1 is associated with high-grade and advanced bladder cancer." (PMID 37123010, 2023). "Our results support a role for FOXA1 as a pioneer factor that regulates chromatin structure, and our findings suggest that global epigenetic reprogramming following FOXA1 loss-of-function contributes to the IFNγ-dominant signature found in the squamous regions of mixed histology bladder cancers." (PMID 36323682, 2022). "We, therefore, hypothesized that increased expression of PD-L1 and other interferon-stimulated genes (ISGs) in bladder cancer cells following FOXA1 loss-of-function is partly a result of changes in H3K27ac modification." (PMID 36323682, 2022). "In addition, the low expression or loss of FOXA1 in basal tumors was described in the development of squamous cell carcinoma in preclinical models of bladder cancer, which is in concordance with the subtype association in the current study." (PMID 32252315, 2020). "FOXA1 is a pioneer transcription modulator and the down-regulation of FOXA1 is implicated as an independent indicator of reduced overall survival in humans with bladder cancer." (PMID 33323547, 2020). "Notably, the function of FOXs may have organizational diversity, as a decrease in FOXA1 expression is associated with tumor infiltration in bladder cancer, whereas overexpression of FOXA1 is associated with good prognosis in triple negative breast cancers." (PMID 36622275, 2023).